IL31 (interleukin 31)
Diseases named in the same sentence as IL31 in open-access papers (continued):
Sharing a sentence is not in itself a finding about the gene and the disease.
psoriasis (39 papers, 2007 to 2026). An autoimmune condition characterized by red, well-delineated plaques with silvery scales that are usually on the extensor surfaces and scalp. "AD is classically associated with dysregulation of the Th2 subset (IL-4, IL-5, IL-13, and IL-31), whereas the Th17 subset (IL-17, IL-21, and IL-22) has been implicated in the pathogenesis of psoriasis." (PMID 40535962, 2025). "Satisfying research results are available indicating a pathogenic link between the IL-33/IL-31 axis and psoriasis and between dysbiosis and psoriasis." (PMID 37509136, 2023). "Particular attention is called to IL-31, which plays a prominent role in the itch sensation in keratinocytes via induction of leukotriene B4, and it is implicated in the pathogenesis of psoriasis." (PMID 36769042, 2023). "Multiple lines of evidence support the role of two classically AD-linked cytokines, TSLP and IL-31 in psoriasis." (PMID 35321329, 2022). "Recent evidence has shown elevated serum levels of IL-31 in psoriasis patients, with distinct IL-31 promoter gene polymorphisms possibly involved in psoriasis pathogenesis." (PMID 36615129, 2022). "On the basis of our study it can be suggested that IL-31 is involved in pathogenesis of psoriasis and the NB-UVB therapy causes alterations in its level." (PMID 23108364, 2013). "Chronic urticaria and psoriasis are associated with elevated serum IL-31 levels." (PMID 41169429, 2025). "The possible involvement of IL-31 in BP-associated pruritus has been proposed, with evidence of elevated levels in BP lesional skin and blister fluid, whereas the role of this pruritogenic cytokine in psoriasis is still elusive." (PMID 36615129, 2022). "This study indicates that itch accompanying psoriasis might be associated with IL-31." (PMID 31281316, 2019). "Elevated IL-31 levels are observed not only in AD but also in other skin conditions, such as prurigo nodularis, psoriasis, and chronic urticaria, and indicate its role as an early pruritogenic mediator in diverse skin diseases." (PMID 40677708, 2025). "Research shows that serum levels of IL-31, a cytokine associated with itch, are elevated in patients with CSU and psoriasis compared to healthy controls." (PMID 39859462, 2025). "Nevertheless, several studies also observed a significant increase in eosinophils and cytokines, such as IL-4, IL-5, IL-9, IL-31, and IL-33, among others, in the blood of patients with psoriasis." (PMID 36865550, 2023). "Interleukin (IL)-31 and IL-33 are both crucial players in the development of AD, and studies are being conducted to elucidate their role in psoriasis." (PMID 37509136, 2023). "Eosinophils are involved in type II immune response, which is related to T helper 2 cells and various interleukins (including IL-4, IL-5, IL-9, IL-13, IL-31, and IL-33, among others), differing from the IL-17/23 axis of psoriasis." (PMID 36865550, 2023). "For instance, in individuals afflicted by psoriasis, levels of IL-31 in serum exhibited a significant reduction following exposure to narrowband ultraviolet radiation." (PMID 37762898, 2023). "The aim of this review is to delve into the link between dysbiosis and the IL-33/IL-31 axis in AD and psoriasis, supporting the idea that dysbiosis can act as an aetiological culprit in the development of skin conditions through immunodysregulation." (PMID 37509136, 2023). "Current knowledge about itch pathology in psoriasis suggests complex interplay between neuropeptides, cytokines and interleukins (expressly IL-31), hormones, and the vascular system." (PMID 35268344, 2022). "The serum level of both TSLP and IL-31 is elevated in patients with pruritic psoriasis, as well the number of IL-31-immunoreactive mast cells at lesional sites, while TSLP expression is increased in the epidermis of psoriatic lesions." (PMID 35321329, 2022).
psoriasis (continued). "Collectively, these data suggested that CB2R didn’t participate in the induction of itch in psoriasis by regulating the expression of IL-31, TSLP and mast cells in mice." (PMID 35173615, 2022). "CB2R didn't participate in the induction of itch in psoriasis by regulating the expression of IL-31, thymic stromal lymphopoietin (TSLP) and mast cells in mouse skins." (PMID 35173615, 2022). "The role of multiple pruritic mediators have been investigated in psoriasis, including neuropeptides, nerve growth factor, IL-31, and TSLP." (PMID 35321329, 2022). "A role for IL-31 in the pathogenesis of psoriasis has been suggested, with elevated levels of serum IL-31 observed in psoriatic patients compared with controls." (PMID 33644103, 2021). "Aside of AD, IL31R overexpression and elevated IL-31 levels are involved in various diseases such as allergic contact dermatitis, psoriasis, bullous pemphigoid, chronic spontaneous urticarial, dermatomyositis, bowel disease and airway hypersensitivity." (PMID 32664385, 2020). "While the role of IL-31 in psoriasis remains to be clarified, current evidence shows that this cytokine plays a major role in BP, chronic spontaneous urticaria and dermatomyositis." (PMID 31281316, 2019). "Our research results show that the concentration of IL-31 in the analyzed group was significantly higher than that in healthy individuals, which confirms its significance in pathogenesis of psoriasis." (PMID 23108364, 2013). "Furthermore, elevated IL‐31 levels have been reported in autoimmune diseases such as psoriasis, systemic lupus erythematosus, dermatomyositis, bullous pemphigoid, and subtypes of pemphigus including the non‐pruritic subtype pemphigus vegetans." (PMID 37632245, 2023). "Still, the direct effect of Staphylococcus Aureus observed on the IL-33/IL-31 axis suggests that the findings observed in AD could also be extended to psoriasis." (PMID 37509136, 2023). "Based on this study, IL-31 seems involved in the pathogenesis of psoriasis, while NB-UVB therapy could prevent the evolution of patches, by lowering the levels of this cytokine." (PMID 35742951, 2022). "IL-31 levels are elevated in patients suffering from chronic prurigo, bullous pemphigoid, cutaneous T-cell lymphoma stasis dermatitis, dermatomyositis, and psoriasis." (PMID 35893400, 2022). "Therefore, although there are disparities in the literature, IL-31 appears to contribute to the induction of itch in psoriasis." (PMID 33182442, 2020). "Recent studies demonstrated that IL-31 gene transcription, its serum level, and the number of IL-31-immunoreactive mast cells at lesional sites were elevated in patients with psoriasis." (PMID 33182442, 2020). "However, it is believed that IL-31 is also involved in pruritic conditions of other origin such as chronic prurigo, psoriasis, and cutaneous T-cell lymphoma." (PMID 30560129, 2018). "NGF and IL-31, which are strongly expressed in the lesional skin of psoriasis, have been shown to promote the growth of sensory nerves, suggesting that the elongation and branching morphogenesis of epidermal nerve fibers are involved in the hypersensitivity of itch in psoriasis." (PMID 33182442, 2020). "This interruption in cytokine signaling effectively reduces the inflammatory response mediated by cytokines such as IL-4, IL-13, IL-31, IL-22, and IFN-γ, which are critical in conditions like AD, psoriasis, and alopecia areata (AA)." (PMID 39610670, 2024). "Compared to HC, AD, and psoriasis, only a few pruritus‐related genes were overexpressed in lesional PN skin, including F2RL3, IL31, IL9, CHAT, EDN1 (endothelin‐1), CHRNA9, and HTR7." (PMID 36789100, 2023). "The noteworthy discordant findings in the context of psoriasis and CSU severity further emphasize the need for comprehensive investigations to unravel the multifaceted role of IL-31 in diverse pruritic conditions." (PMID 37762898, 2023).
psoriasis (continued). "Recent studies demonstrated that IL-31 and TSLP appear to be partially involved not only in the pathogenesis of psoriasis, but also in the induction of itch in psoriasis." (PMID 35173615, 2022). "In psoriasis, it has been shown that 20 repeated suberythemogenic NB-UVB treatments significantly reduced IL-31 serum levels." (PMID 30560129, 2018). "Although not prominently studied in psoriasis (Pso), since the main actors in its pathogenesis are Th1 and Th17 interleukins, IL-31 has shown, over the years, a certain role in Pso itching, leading to the concept of “itchscriptome”." (PMID 35742951, 2022). "It was shown that levels of IL-31 were significantly elevated in pruritic lesional skin of patients with AD compared to nonpruritic lesional skin of patients with psoriasis." (PMID 32664385, 2020). "It was originally thought that IL-31 does not play a role in psoriasis, based on comparisons of cellular expressions of the cytokine (both at mRNA level and immunoreactivity) together with controls." (PMID 31281316, 2019). "However, there were no marked differences in both epidermal and dermal IL‐31 expressions in lesional PN skin compared with lesional AD, lesional psoriasis, and normal skin from HC, consistent with previous reports." (PMID 36789100, 2023). "On balance, and despite the possibility that it may contribute to pruritic forms of the disease, the currently published literature does not yet provide a clear consensus regarding the role of IL-31 in psoriasis per se." (PMID 31281316, 2019).
asthma (25 papers, 2008 to 2025). "To determine the effects of IL-31 on the expression of asthma-associated genes, we quantified the expression of genes associated with inflammation (IFNγ, TNF-α, IL-6, and IL-17) and Th2 responses (IL-4, IL-13, ARG1, MUC4, and MUC5AC)." (PMID 38081868, 2023). "Although IL-31 has been implicated in asthma, the exact contribution of the IL-31 receptor (IL-31RA) signalling to airway hyperresponsiveness remains unexplored." (PMID 38081868, 2023). "In patients with asthma, the IL-31 single nucleotide polymorphisms (SNPs) were significantly correlated with total serum levels of IgE18." (PMID 26956917, 2016). "The mechanism underlying nemolizumab-induced cAEs and asthma remains unclear, but activation of Th2-driven inflammation following IL-31 blockade has been proposed." (PMID 41393760, 2025). "The current data may provide insight into the underlying pathogenesis of asthma, in which IL-31 has an important pathogenic role." (PMID 26956917, 2016). "In conclusion, low levels of 25(OH) Vit D might represent a risk factor for the development of concomitant asthma and rhinitis in children with allergic disease of the airways independently of IL-31/IL-33 Th2 activity." (PMID 25061262, 2014). "The present study for the first time suggests that nemolizumab potentially induces activation of well-controlled asthma through the suppression of IL-31, which has a critical role for asthma inactivation." (PMID 40538782, 2025). "IL-31 was reported to be an indicator of asthma severity with a proinflammatory function positively correlated with Th2 cytokines in peripheral blood." (PMID 40538782, 2025). "IL-31 seems to have a dual role in asthma, a pro-inflammatory one in the early stage and anti-inflammatory action in the late one." (PMID 38397331, 2024). "IL-31 has recently been described as the main cytokine involved in allergies, such as cutaneous allergic reactions and asthma." (PMID 36902810, 2023). "In the last years, the interest in the study of IL-31 has grown concerning, in addition to skin conditions, Th2-mediated airways diseases, especially allergic rhinitis and asthma." (PMID 35742951, 2022). "Another strain of research regarding bronchial epithelium of children with asthma found some correlation with decreased levels of 25-OH vitamin D and higher levels of IL-31, but further research should be carried out to assess the possible therapeutic options." (PMID 35742951, 2022). "IL-31 has also been shown to play relevant roles in allergic contact dermatitis, urticaria, mastocytosis, allergic rhinitis and asthma." (PMID 33644104, 2021). "Studies have shown that levels of IL-31 mRNA and protein are elevated in patients with allergic asthma, and expression of both IL-31 and IL-31R are increased in the bronchial tissue of patients with severe asthma." (PMID 33644103, 2021). "They demonstrated that serum and BALF IL-31 levels were significantly elevated in patients with asthma compared with controls." (PMID 31766607, 2019). "Serum IL-31 levels were significantly elevated in patients with asthma and correlated positively with Th2 type cytokines IL-5 and IL-13, asthma severity or total serum IgE." (PMID 30647024, 2019). "In particular, the activation of the IL-33/ST2-involving Th2/IL-31 immune response has a crucial role for the development of allergic inflammation, such as in asthma." (PMID 31766607, 2019). "Some researches demonstrated that the expression of IL-31 and IL-31R was increased in allergic diseases, especially in asthma." (PMID 29713240, 2018). "Our data showed that expressions of IL-31RA and OSMR in lung sections were more pronounced in more severe forms of asthma and positively correlated with serum IL-31 levels." (PMID 26956917, 2016). "Our data showed that serum and BALF IL-31 levels were significantly elevated in patients with asthma compared with controls." (PMID 26956917, 2016).
asthma (continued). "Patients with uncontrolled asthma had statistically higher serum IL-31 levels than patients with partly controlled (p < 0.01) and completely controlled asthma (p < 0.001)." (PMID 26956917, 2016). "Our study indicated that serum IL-31 levels were increased in patients with asthma, as compared with control subjects, and correlated with the severity of asthma." (PMID 26956917, 2016). "In order to make a solid conclusion of the crucial roles of IL-31 in asthma, we further assessed the IL-31 receptor IL-31RA and OSMR in the tissues." (PMID 26956917, 2016). "In the present study, we explored the potential role of IL-31 measurement in the management of asthma." (PMID 26956917, 2016). "In summary, we have shown that IL-31 is found in increased quantities in the serum and lungs of patients with asthma, in whom the protein levels correlate positively with the severity of disease and total IgE and inversely with lung function." (PMID 26956917, 2016). "The present study provides new knowledge about the potential role of IL-31 in asthma that contributes to further understanding of its pathophysiology." (PMID 26956917, 2016). "We found that circulating levels of IL-31 in the moderate-to-severe and uncontrolled groups were significantly higher than those in the mild and controlled groups, which suggested that serum levels of IL-31 correlate with asthma severity." (PMID 26956917, 2016). "We quantified IL-31 levels in the serum of patients with asthma (n = 44), as well as in controls (n = 22)." (PMID 26956917, 2016). "In an animal model of asthma antigen challenge increases the expression of IL-31 in lung epithelium and BAL cells." (PMID 18315837, 2008). "In addition to the key role of IL-31 in pruritus, large amounts of IL-31 were also found in the serum and tissues of patients with inflammatory bowel disease, Crohn’s disease, rhinitis, and asthma." (PMID 40443235, 2025). "There are some reports on the role of IL-31 regarding asthma." (PMID 40538782, 2025). "An increased IL-31 could lead to a Th2-dominant inflammation in the early stage, but with late anti-inflammatory action in asthma It is also a potential biomarker for the phenotypic classification of viral bronchiolitis, depending on the type of virus." (PMID 38397331, 2024). "Overall, other studies demonstrate that IL-31 correlates to asthma and allergic rhinitis, but may have many limitations, especially regarding the number of patients recruited, and some are discordant with each other." (PMID 35742951, 2022). "Given the role of IL-31 signaling in the development of itch it is interesting to speculate whether IL-31 may also be involved in the stimulation of sneezing, coughing or bronchial hyperreactivity." (PMID 33644104, 2021). "Serum IL-31 levels were also found to positively correlate with asthma severity and IgE levels." (PMID 33644103, 2021). "IL31 is of major interest to our study as it is a Th2 cytokine overexpressed in asthma 35,36." (PMID 32317758, 2020). "Recently, the relationship between asthma and IL-31 was also studied." (PMID 31766607, 2019). "To explore the dynamic changes in IL-31 and IL-31RA in vivo, we established an asthma mouse model." (PMID 30647024, 2019). "IL-31 is a Th2 cytokine, to determine whether its serum concentration is correlated with other asthma related Th2 cytokines in asthma, we further measured the Th2 related cytokines IL-5, IL-13 and thymic stromal lymphopoietin (TSLP)." (PMID 26956917, 2016). "Collectively, these data further confirmed that the levels of IL-31 is useful indicator for asthma." (PMID 26956917, 2016). "Moreover, IL-31 levels were significantly increased in the BALF of patients with asthma compared with the controls." (PMID 26956917, 2016). "IL-31 levels may therefore be a useful adjunct in the objective identification and management of severe asthma." (PMID 26956917, 2016).